CNMD (chondromodulin)
Description:
Bifunctional growth regulator that stimulates the growth of cultured chondrocytes in the presence of basic fibroblast growth factor (FGF) but inhibits the growth of cultured vascular endothelial cells. May contribute to the rapid growth of cartilage and vascular invasion prior to the replacement of cartilage by bone during endochondral bone development. Inhibits in vitro tube formation and mobilization of endothelial cells. Plays a role as antiangiogenic factor in cardiac valves to suppress neovascularization.
Synonyms: ChM-I; LECT1; MYETS1; CHM1; BRICD3
Tractability: Antibody: UniProt places it where antibodies can reach, with medium confidence; UniProt predicts a signal peptide or a membrane-spanning region; its Gene Ontology location is reachable by antibodies, with medium confidence.
Gene: Protein-coding gene on chromosome 13 (52,703,258 to 52,740,089, reverse strand). Ensembl gene ENSG00000136110.
Subcellular location: Secreted, extracellular space, extracellular matrix (Chondromodulin-1); Endomembrane system (Chondrosurfactant protein)
Gene Ontology:
Biological process: negative regulation of angiogenesis; negative regulation of endothelial cell proliferation; proteoglycan metabolic process; skeletal system development
Cellular component: endomembrane system
Genetic constraint (gnomAD): Loss-of-function variants: 25 observed, 28.51 expected, observed/expected ratio (o/e) 0.88, 90% interval 0.64 to 1.23. The upper end of that interval is the gene's LOEUF score, 1.23, which puts it in group 5 of 6, group 1 being the genes least tolerant of losing a copy. Missense variants: 352 observed, 371.74 expected, observed/expected ratio (o/e) 0.95, 90% interval 0.87 to 1.03. Synonymous variants: 146 observed, 129.29 expected, observed/expected ratio (o/e) 1.13, 90% interval 0.99 to 1.3.
Homologues: Orthologues: chimpanzee CNMD (99% identical), macaque CNMD (97% identical), dog CNMD (93% identical), pig CNMD (92% identical), guinea pig CNMD (89% identical), mouse Cnmd (89% identical), rat Cnmd (89% identical), rabbit CNMD (84% identical), tropical clawed frog cnmd (68% identical), zebrafish cnmd (40% identical). Paralogues in human: TNMD (32% identical).
Diseases named in the same sentence as CNMD in open-access papers:
CNMD is named in the same sentence as 37 diseases in open-access papers, as found by Europe PMC text mining. Sharing a sentence is not in itself a finding about the gene and the disease. The quoted sentences say what the papers report.
Ewing sarcoma (6 papers, 2011 to 2020). A small round cell tumor that lacks morphologic, immunohistochemical, and electron microscopic evidence of neuroectodermal differentiation. "We have described the BRICHOS chaperon domain containing endochondral bone protein Chondromodulin-I (CHM1) being directly up-regulated by the Ewing sarcoma (ES) causing the fusion oncogene product EWS-FLI1." (PMID 27281613, 2016). "Chondromodulin-I (CHM1) is a downstream target of the driver oncogene EWS-FLI1 in Ewing sarcoma and promotes metastasis." (PMID 30171420, 2018). "The endochondral bone protein Chondromodulin-I (CHM1) provides oncogene addiction in Ewing sarcoma (ES)." (PMID 27281613, 2016). "Chondromodulin-I is an ideal target as it plays a critical role in Ewing sarcoma pathogenesis by being upregulated by the Ewing sarcoma fusion oncogene EWS-FLI1 and by maintaining an undifferentiated invasive phenotype and metastatic spread of the sarcoma cells." (PMID 32123937, 2020). "Here, we test the specific recognition and lytical potential of allo-restricted CD8+ T cells against Ewing tumour (ET) associated antigens Enhancer of Zeste, Drosophila Homolog 2 (EZH2), and Chondromodulin-I (CHM1) identified through previous microarray analysis." (PMID 21407224, 2011). "Beta-3-adrenergic receptor (ADRB3) as well as chondromodulin-1 (CHM1) are over-expressed in Ewing Sarcoma (ES) but not on T cells." (PMID 27447745, 2016).
epilepsy (1 paper, 2025). A brain disorder characterized by episodes of abnormally increased neuronal discharge resulting in transient episodes of sensory or motor neurological dysfunction, or psychic dysfunction. "We identified three methylation biomarkers (IL1RAP, HIPK2 and CNMD) and validated their utility in differentiating FCD IIa from IIb in a larger replication study and an independent cohort of patients with epilepsy." (PMID 40860011, 2025).
tumor (13 papers, 2009 to 2025). "Chondromodulin-1 (ChM-1) is an extracellular matrix protein that plays crucial roles in tumor cell growth and angiogenesis in vertebrates and humans." (PMID 29439497, 2018). "Here, we analyzed one of the BRICHOS domain‐containing genes, leukocyte cell‐derived chemotaxin 1 (also known as chondromodulin 1; CHM1; CNMD), for its function in chondro‐osseous tumor growth and invasiveness." (PMID 28319320, 2017).
CNMD also shares sentences with these, for which no sentence is quoted: cancer (7 papers); hydatidiform mole (4); osteosarcoma (4); chondrosarcoma (3); neuroblastoma (3); breast carcinoma (2); cognitive deficits (2); infection (2); osteoarthritis (2); acute lymphoblastic leukaemia (1); cervical cancer (1); chlamydial infection (1); choroideremia (1); colon adenocarcinoma (1); complex hereditary spastic paraplegia (1); dementia (1); endocarditis (1); gastric cancer (1); graft versus host disease (1); heart disease (1); infective endocarditis (1); Infertility (1); leukemia (1); malignant tumor of bone (1); medulloblastoma (1); melanoma (1); microcephaly (1); multiple endocrine neoplasia (1); nasopharyngeal carcinoma (1); psoriasis (1).
A further 4 diseases each share a sentence with CNMD in 1 paper.